CD48 (CD48 molecule)
Description:
Glycosylphosphatidylinositol (GPI)-anchored cell surface glycoprotein that interacts via its N-terminal immunoglobulin domain with cell surface receptors including CD244/2B4 or CD2 to regulate immune cell function and activation. Participates in T-cell signaling transduction by associating with CD2 and efficiently bringing the Src family protein kinase LCK and LAT to the TCR/CD3 complex. In turn, promotes LCK phosphorylation and subsequent activation. Induces the phosphorylation of the cytoplasmic immunoreceptortyrosine switch motifs (ITSMs) of CD244 initiating a series of signaling events that leads to the generation of the immunological synapse and the directed release of cytolytic granules containing perforin and granzymes by T-lymphocytes and NK-cells.
Synonyms: SLAMF2; BCM1; BLAST1; BLAST; mCD48; hCD48; MEM-102
Tractability: Antibody: UniProt places it where antibodies can reach, with high confidence; its Gene Ontology location is reachable by antibodies, with high confidence; UniProt predicts a signal peptide or a membrane-spanning region; the Human Protein Atlas places it where antibodies can reach. PROTAC: ubiquitination databases record sites on it; its protein half-life has been measured.
Gene: Protein-coding gene on chromosome 1 (160,678,746 to 160,711,831, reverse strand). Ensembl gene ENSG00000117091.
Subcellular location: Cell membrane; Membrane raft; Secreted
Subcellular location (Human Protein Atlas): Plasma membrane; Cytosol; Nucleoli fibrillar center; Predicted to be secreted
Pathways (Reactome):
Hemostasis: Cell surface interactions at the vascular wall
Gene Ontology:
Molecular function: protein binding; receptor ligand activity
Biological process: natural killer cell activation; defense response; immune response; leukocyte activation; signal transduction
Cellular component: extracellular exosome; extracellular region; membrane; membrane raft; plasma membrane
Genetic constraint (gnomAD): Loss-of-function variants: 20 observed, 22.18 expected, observed/expected ratio (o/e) 0.9, 90% interval 0.63 to 1.31. The upper end of that interval is the gene's LOEUF score, 1.31, which puts it in group 5 of 6, group 1 being the genes least tolerant of losing a copy. Missense variants: 303 observed, 300.06 expected, observed/expected ratio (o/e) 1.01, 90% interval 0.92 to 1.11. Synonymous variants: 108 observed, 114.52 expected, observed/expected ratio (o/e) 0.94, 90% interval 0.81 to 1.11.
Homologues: Orthologues: chimpanzee CD48 (90% identical), macaque CD48 (82% identical), pig CD48 (54% identical), guinea pig CD48 (51% identical), dog CD48 (49% identical), mouse Cd48 (47% identical), rat Cd48 (44% identical), zebrafish si:cabz01074946.1 (18% identical). Paralogues in human: SLAMF1 (20% identical), SLAMF8 (20% identical), CD244 (19% identical), CD84 (19% identical), SLAMF6 (17% identical), SLAMF9 (17% identical), LY9 (16% identical), SLAMF7 (15% identical), CD2 (13% identical).
Diseases named in the same sentence as CD48 in open-access papers:
CD48 is named in the same sentence as 106 diseases in open-access papers, as found by Europe PMC text mining. Sharing a sentence is not in itself a finding about the gene and the disease. The quoted sentences say what the papers report.
glioma (16 papers, 2021 to 2025). A benign or malignant brain and spinal cord tumor that arises from glial cells (astrocytes, oligodendrocytes, ependymal cells). "CD48 upregulation in gliomas was associated with enhanced macrophage and T cell infiltration, the IDHwt status of mesenchymal subtype gliomas and a worse outcome." (PMID 40895574, 2025). "CD48, an immune checkpoint that has been reported associated with poor prognosis in gliomas, was also down-regulated in T cell population of anti-Tnfrsf14 group samples." (PMID 39085878, 2024). "FPR3 correlated positively with immune checkpoint genes, particularly PD-1 and CD48, suggesting its potential regulation of diverse immunological checkpoints in gliomas." (PMID 39445161, 2024). "A major study also connected the elevated expression of CD48 with a poor prognosis for glioma patients, albeit the overexpression of CD48 makes these tumor cells an optimized target for NK cell cytotoxicity." (PMID 37609636, 2023). "It has been reported that CD48 can be used as a prognostic marker for diseases such as lung cancer, glioma, and colon cancer." (PMID 37349706, 2023). "CD48 has been reported to be involved in antigen processing and presentation, T cell co-stimulation, and T cell receptor signaling pathways in glioma (GBM)." (PMID 35421944, 2022). "CD48 is a key molecule of immunomodulation affecting prognosis in glioma, and combining CD48 blockade with PD-L1 may be a promising immunotherapy approach for specific subpopulations of glioma." (PMID 40761790, 2025). "Meanwhile, CD48 had also been studied and its high expression in gliomas might lead to a lower survival rate, while for CD200, its higher expression might prolong microglia activation and tumor growth." (PMID 39039366, 2024). "Although, CD48 is expressed on a variety of hematopoietic cells, upregulated expression is seen in a few hematological malignancies, for example, multiple myeloma and glioma." (PMID 37609636, 2023). "Interestingly, one study evaluated CD48 together with PD-L1, an immune checkpoint mechanism in glioma, suggesting that these two upregulated signaling pathways with anti-Aβ antibody exposure may trigger acute immunomodulatory response first." (PMID 39741000, 2025). "Correlation analysis revealed that the expression levels of CD48, CD276, and CD274 proteins in glioma were significantly correlated with their mRNA levels (r > 0.6, p < 0.05)." (PMID 40606983, 2025). "Previous studies have identified different immune checkpoint molecules in gliomas, such as CTLA-4, TIM-3, PD-1, CD48, and LAG3." (PMID 35832194, 2022). "Thus, we attempted to analyze certain immune checkpoints such as CD274 (PDL1), CD48, and HAVCR2 (TIM-3), which have been proven to play negative roles in gliomas." (PMID 40606983, 2025).
leukemia (13 papers, 2016 to 2025). A malignant (clonal) hematologic disorder, involving hematopoietic stem cells and characterized by the presence of primitive or atypical myeloid or lymphoid cells in the bone marrow and the blood. "Elevation of circulating soluble CD48 levels is observed in inflammatory conditions such as arthritis, leukemia or EBV infection." (PMID 38686386, 2024). "The leukemia-containing clusters were found to have a low expression of CD48 and CD58, the genes coding for activating ligands that bind CD2." (PMID 35349491, 2022). "The authors found that TGF-β significantly decreased NK cell killing of leukemia cell lines secondary to leukemia cell downregulation of the NK cell ligand CD48 as well as decreased ICAM-1 binding affinity resulting in impaired effector-target interaction." (PMID 33766099, 2021). "Abdelhamed and colleagues described the ability of leukemia-blast–derived EVs to enter murine HSCs (Lineage–cKit+Sca1+CD150+CD48–), resulting in suppressed protein synthesis and increased cell quiescence, thereby demonstrating the reversibility of murine HSPC dysfunction under leukemia stress." (PMID 36106632, 2022). "Research has shown that the hypomethylation agent (HMA) decitabine can upregulate the level of ICAM-1(CD54) and CD48 on AML cells, thereby activating NKs to kill leukemia cells while reversing immune evasion by leukemia cells." (PMID 40008144, 2025). "Whereas HSCs are Lin− Sca1+cKit+CD48−CD150+ and MPP linage is Lin− Sca1+cKit+CD48+CD150−, the ML23 leukemia cell linage is cKit−/+Sca1+CD150+CD48−/+, which suggests heterogeneous subpopulations with respect to the cKit and CD48 markers." (PMID 33602907, 2021). "HMGN1-OE leukemias were enriched for LSK-like cells and particularly for the LSK subset having a multipotent progenitor (MPP)-like phenotype (Lin− CD117+ Sca-1+ CD150+ CD48−)." (PMID 32179749, 2020). "Three subsets of LKS+ HSCs, namely, LT-HSCs (LKS+CD34− or LKS+CD150+CD48−), ST-HSCs (LKS+CD34+Flk2−) and MPPs (LKS+CD34+Flk2+), all suffered progressive decreases in absolute numbers during leukemia development." (PMID 27585558, 2016). "RT1(9a) Kit+Sca1−/lowCD34− AML cells exhibited variable combinations of FcgR, CD48, and CD14, suggesting that leukemias may have developed from different subclones within that compartment." (PMID 35921412, 2022). "In patient 1, in whom most of the expanded and persistent NK cells exhibited a mature cytotoxic CD56dimCD16+ phenotype, the absence of expression of CD48 and CD58 on relapsed leukemia could suggest a resistance mechanism." (PMID 35349491, 2022).
breast carcinoma (11 papers, 2014 to 2025). "In our analysis, we observed a positive correlation with both γδ T cell abundance and CD48 expression in breast cancer." (PMID 41458604, 2025). "A total of 88 candidate genes related to breast cancer prognosis were screened, of which CD48, SLAMF7, SLAMF1, IGLL1, IGHA1, and LRRC8A were key genes." (PMID 38388382, 2024). "The results showed that IGLL1, SLAMF7, SLAMF1, CD48, and LRRC8A were closely associated with immune infiltration in breast cancer (p < 0.05)." (PMID 38388382, 2024). "The first one shows that the transcriptome signals obtained from TBX21 are highly correlated with downstream signal of the Up gene CD48 (r = 0.86) in the breast cancer case (n = 1093)." (PMID 31227749, 2019). "On the other hand, CD48, SLAMF1, and SLAMF7 were highly expressed in HER2 + and triple-negative breast cancer (TNBC), and IGLL1 was highly expressed in ER + and TNBC tissues; These six key genes are closely associated with immune infiltration in breast cancer." (PMID 38388382, 2024). "In an analysis of the TCGA database, mRNA relative expression levels of GZMK (log2(TPM + 1)) were correlated with CTLA4, PD-1, PD-L1, CD48, and CCR7 in patients with breast cancer." (PMID 38833021, 2024). "In breast cancer, the high expression of SLAMF1, SLAMF7, CD48, and IGLL1 is positively correlated with the infiltration of B cells, CD8 + T cells, CD4 + T cells, macrophages, neutrophils, and dendritic cells." (PMID 38388382, 2024). "We evaluated the correlation between the expression of IGLL1, SLAMF7, SLAMF1, CD48, and LRRC8A and the immune infiltration profile in breast cancer using data downloaded from TCGA." (PMID 38388382, 2024). "In three different types of breast cancer cells, differential expression was also observed in genes including HERV-K_1q23.3, CD48, SLAMF1, SLAMF7, HERV-K_22q11.23, IGLL1, HERV-K_9q34.11, and LRRC8A." (PMID 38388382, 2024). "When comparing biopsies of distant metastases of non-inflammatory breast cancer, CD48 was one of six downregulated genes compared to the primary invasive ductal carcinomas." (PMID 38476238, 2024). "Furthermore, PD-L1, CD112, TNFRSF14, TNFSF4, TNFSF18, CD48, and LGALS9 were analyzed for abnormal expression patterns in breast carcinomas." (PMID 34545132, 2021). "SLAMF2/CD48 has not been studied extensively in breast cancer." (PMID 38476238, 2024). "Further research is needed to investigate these results, and the results of the drug sensitivity analysis indicated that IGLL1, SLAMF7, SLAMF1, CD48, and LRRC8A might decrease sensitivity to specific chemotherapy drugs, further affecting the treatment efficacy for breast cancer." (PMID 38388382, 2024). "However, other co-inhibitory molecules CD48, PD-L1, and PD-L2 were not significantly different between breast cancer and normal breast tissue LECs." (PMID 36362253, 2022).
hepatocellular carcinoma (11 papers, 2018 to 2025). A malignant tumor that arises from hepatocytes. "CD48 can participate in GDF15-induced regulatory T cell generation and enhanced function, thereby regulating hepatocellular carcinoma-associated immunosuppression." (PMID 37285836, 2023). "Monocytes isolated from hepatocellular carcinoma have high CD48 expression and blocking the 2B4-CD48 interaction decreased NK cell activation and exhaustion." (PMID 38090565, 2023). "Furthermore, studies in hepatocellular carcinoma have identified CD48 as the first GDF15 receptor discovered within the immune system." (PMID 40837873, 2025). "In hepatocellular carcinoma, CD48/2B4 interactions could mediate the dysfunction of monocyte/macrophage-elicited natural killer cell." (PMID 35237300, 2022). "Some scholars detected a decrease in CD48 expression in hepatocellular carcinoma cells." (PMID 31888692, 2019). "Moreover, CD48 could act as an immunosuppressive mediator by enhancing the function of Tregs in hepatocellular carcinomas." (PMID 37252189, 2023). "Conversely, in human hepatocellular carcinoma (HCC), CD48‐overexpressing monocytes within the TME engage CD244+ NK cells, leading to transient activation followed by rapid exhaustion and cell death." (PMID 40959206, 2025).
myeloma (11 papers, 2011 to 2026). "We probe crosslinking patterns suggesting multiple myeloma-specific CD48 and AML-specific integrin α1/β4 heterodimer conformations." (PMID 42239335, 2026). "The natural characteristics of multiple myelomas showed therapeutic effects of a monoclonal antibody against CD48, which is highly expressed on plasma cells, implying that the 2B4–CD48 interaction plays a role in tumor immunity." (PMID 39886466, 2025). "CD48, or Signaling lymphocyte activation molecule family member 2 (SLAMF2), is a glycosylphosphatidylinositol-anchored membrane protein expressed on myeloma cells that participates in activation and differentiation pathways." (PMID 37111346, 2023). "WB collected from healthy donors (HDs) and patients with multiple myeloma (MM) was stimulated with P815-ULBP1+CD48 cells combined with IL-2." (PMID 33143099, 2020). "CD48 is expressed only on certain hematopoietic stem/progenitor cells and is not present on red blood cells or platelets, which has already been confirmed as a novel molecular target for antibody therapy in multiple myeloma." (PMID 38919521, 2024). "Anti-CD48 monoclonal antibody can inhibit myeloma cell growth in vivo, suggesting it could be effective in treating MM patients." (PMID 31842518, 2019). "Recently, CD48 was found to be expressed on more than 90% of plasma cells from myeloma patients at higher levels than those observed on normal lymphocytes, although it is unknown whether this elevated expression could have a negative impact on T cell reactivity." (PMID 25614821, 2015). "To evaluate which of these proteins is more highly expressed at the myeloma cell surface, we used calibrated flow cytometry to measure absolute antigen density of both CD38 and CD48 expression." (PMID 35840578, 2022). "It was reported that most myeloma cells from NDMM and RRMM patients express high levels of SLAMF2 (CD48)." (PMID 31842518, 2019). "Myeloma-bearing mice were treated with a low dose of whole body irradiation and combinations of blocking antibodies to PD-L1, LAG-3, TIM-3, CD48 (the ligand for 2B4) and CTLA4." (PMID 25614821, 2015). "Validating our strategy, we identified nearly all known canonical diagnostic markers and immunotherapeutic targets in myeloma, including BCMA, CD138/SDC1, CD38, CD56, SLAMF7/CS-1, CD46, Integrin-b7 (ITGB7), CD74/HLA-DR, TACI, CD48/ SLAMF2, and LY9/CD229." (PMID 36311892, 2022). "Therefore, we used calibrated flow cytometry on both cell lines and primary myeloma bone marrow aspirate samples from relapsed/refractory myeloma patients to assess CD38 and CD48 density." (PMID 36311892, 2022). "Anti-CD48 administered alone or with anti-PD-L1 failed to have any impact on the elimination of myeloma." (PMID 25614821, 2015). "Notably, across these lines we detected almost all of the major immunotherapy targets in myeloma, as well as canonical flow cytometry markers for plasma cells: BCMA, CD138/SDC1, CD38, CD56, SLAMF7/CS-1, CD46, Integrin-b7 (ITGB7), CD74/HLA-DR, TACI, CD48/SLAMF2, and LY9/CD229." (PMID 35840578, 2022). "Despite upregulation of 2B4 on T cells with increasing myeloma burden, which has also been observed on CD8 and CD4 T cells in a mouse pancreatic cancer model, blockade of PD-L1 plus the ligand for 2B4, CD48, did not provide any additional benefits over PD-L1 blockade alone." (PMID 25614821, 2015).
lymphoma (10 papers, 1991 to 2025). A malignant (clonal) proliferation of B- lymphocytes or T- lymphocytes which involves the lymph nodes, bone marrow and/or extranodal sites. "Moreover, TGF-β stimulation in MEG-01 cells, which are derived from a CML patient having BCR-ABL fusion protein, and in U937 cells, which are derived from lymphoma, results in suppressed CD48 expression levels and lower susceptibility to NK targeting." (PMID 33602907, 2021). "It was suggested that anti-SLAMF2/CD48 antibodies may be useful in the treatment of a number of diseases, including lymphoid leukemias and lymphomas." (PMID 38612827, 2024). "Additional markers that may be helpful for MRD assessment include CD99, which may be overexpressed in T-lymphoblastic leukemia/lymphoma compared with normal T cells, and CD48, which exhibits reduced expression in T-lymphoblastic leukemia/lymphoma compared with normal T cells." (PMID 40227608, 2025). "Microarray analyses revealed significant upregulation of a multitude of NK-activating and costimulatory ligands across varied b-NHL cell lines and primary lymphoma cells, including ULBP1, CD72, CD48, and SLAMF6." (PMID 29312292, 2017). "Thus, while CD48+ B-EBV and lymphoma B-cells devoid of NKG2D and DNAM-1 ligands were resistant to lysis, the preferential usage of these receptors allowed XLP-1 NK cells to kill lymphomas that expressed sufficient amounts of the specific ligands." (PMID 24795715, 2014).